SPP1 (secreted phosphoprotein 1)
Diseases named in the same sentence as SPP1 in open-access papers (continued):
Sharing a sentence is not in itself a finding about the gene and the disease.
tumor (continued). "Simultaneously, we identified a pronounced expression of the TF HIF1A, known to facilitate tumor immune escape within SPP1+ M1 macrophages, a population that was notably abundant in the NpCR group." (PMID 39170612, 2024). "The results showed that SPP1 + macrophages were in closer proximity to tumor cells than SPP1- macrophages." (PMID 39696410, 2024). "Within this structure, POSTN+ fibroblasts and SPP1+ macrophages form a barrier that shields tumor cells from immune cell attacks." (PMID 39716897, 2024). "LPS can facilitate tumor cell adhesion by upregulating the oncogenic gene SPP1, thus promoting metastasis of malignant tumors, especially NSCLC." (PMID 39610830, 2024). "Single-cell RNA sequencing analysis has revealed that SPP1 is more highly expressed in monocyte-derived TAMs compared to resident macrophages/TAMs, further highlighting its role in tumor development." (PMID 39727934, 2024). "CD8+ MAIT cells recruit a good subset of macrophages (FOLR2+) to infiltrate into the tumor microenvironment but are transformed to low‐phagocytosis SPP1+ subsets due to the oxygen competition with proliferating tumor cells nearby." (PMID 39716897, 2024). "The significant function of SPP1+ macrophages across various cancer contexts, especially in terms of tumor progression, metastasis, and the modulation of immune responses, is noteworthy." (PMID 38600248, 2024). "Future work is needed to study other organ sites enriched for SPP1+ macrophages-tumor-reactive CD8 T cells interactions." (PMID 39372792, 2024). "Our study illuminates the role of CEBPB in GBM subcluster 6, demonstrating its ability to recruit and polarize macrophages into the M2 phenotype by regulating the secretion of CCL2 and SPP1 by tumor cells." (PMID 38994023, 2024). "High variability genes in monocyte_C02 cells, including CXCL8, TNFAIP6, CXCL3, and SPP1, indicate a potential role in tumor promotion." (PMID 38711918, 2024). "Specifically, tumor-derived SPP1 acted on lung epithelial cells via the CD44/CXCL1 axis to increase local neutrophil infiltration." (PMID 39529085, 2024). "When NAMPT expression was further analyzed in two groups of TAMs in the tumor tissues, SPP1+TAMs showed a greater increase in NAMPT expression with respect to monocytes compared to C1QC+TAMs." (PMID 38308188, 2024). "We also identified another tumor-specific community occupied by pro-tumorigenic states, such as pEMT, epithelial T cell exclusion program, SPP1+ macrophage, and desmoplastic fibroblast." (PMID 38744958, 2024). "In our study, SPP1 was found to be highly expressed in myeloid cells in tumor tissues, especially in TAMs." (PMID 39726047, 2024). "In summary, the phenotype of SIRPA-positive Macro-SPP1 was similar to the macrophages engulfing tumor cells described previously." (PMID 39696410, 2024). "Since SPP1+ Macs are almost universally present in tumor tissues, we next investigated SPP1 expression in myeloid cells." (PMID 39726047, 2024). "The spatial analysis showed that SPP1 + SIRPα + macrophages were in closer proximity to tumor cells compared with SPP1- macrophages." (PMID 39696410, 2024). "In summary, similar to the human scRNA-seq results, an enriched Spp1 macrophage population was seen in intrahepatic TILs which correlated with tumor size and showed a distinct phenotype from the M2 macrophages." (PMID 39372792, 2024). "The expression of the top candidate biomarker, SPP1, was significantly higher in tumor tissue compared to matched normal tissue (p = 0.0008) in keeping with NanoString gene expression analysis." (PMID 39409192, 2024). "SPP1 + SIRPα + macrophages showed close spatial distance to tumor cells and positively correlated with PD1 + CD8 + T cells." (PMID 39696410, 2024). "In accordance with these findings, we found that SPP1 was upregulated in tumor tissue compared with matched para-cancerous tissues and was more highly expressed in the tissues and serum of patients with lung metastasis." (PMID 39529085, 2024).
tumor (continued). "The relationship between SPP1 and HCC can be summarized as follows, the interaction between SPP1 + macrophages and cancer-associated fibroblasts within the HCC microenvironment established a tumor immune barrier that impeded the efficacy of immunotherapy." (PMID 39066845, 2024). "Consistent with the in vitro results, the inhibitory effects of targeting NOTCH3 on tumor growth and metastasis were counteracted by SPP1 overexpression." (PMID 39557868, 2024). "SPP1 promotes fibrosis and is critically involved in the fibroblast to myofibroblast transformation, which participates in tumor proliferation, angiogenesis, and metastasis." (PMID 38987572, 2024). "SPP1 + TAMs and C1QC + TAMs, associated with tumor angiogenesis and phagocytosis respectively, highlight the potential of targeting distinct TAM subpopulations to influence immunotherapy effectiveness." (PMID 39068459, 2024). "On the contrary, we identified 11 significantly active signaling pathways in tumor cell clusters, including the SPP1 signaling pathway." (PMID 38191424, 2024). "To investigate the role of SPP1 signaling on tumor cells, we analyzed 4252 tumor cells from ccRCC samples and 1604 epithelial cells from normal samples." (PMID 38191424, 2024). "SPP1 is overexpressed in COAD, significantly enhancing tumor cell invasion and metastasis, and is associated with poor prognosis." (PMID 39850875, 2024). "Anti-TNF-α and anti-IL-1β in SPP1-OE supernatant had similar effect on tumor cells compared with VGX-1027." (PMID 39726047, 2024). "To investigate the spatial organization of CSC and Macro_SPP1, we conducted spatial transcriptomics sequencing using tumor tissue sections from eight HCC patients." (PMID 38521868, 2024). "Here, we obtained scRNA-seq data from 5 pairs of HNSCC clinical samples and revealed that tumor-specific SPP1 + Macs were correlated with poor prognosis." (PMID 39726047, 2024). "The number of TAMs increased, and the expression of SPP1 gene was upregulated and has a core role in tumor progression." (PMID 38787372, 2024). "The bulk RNA‐seq data from the ICC cohort at Fudan University corroborate the positive correlation between the enrichment of the SPP1+ macrophage signature and the elevated levels of both the tumor stemness signature and CD44 expression." (PMID 39716897, 2024). "SPP1 plays a significant role in tumor progression, invasion, metastatic ability, and poor prognosis." (PMID 39850883, 2024). "The results indicate that the enriched spots of SPP1+ macrophage on the spatial transcriptome are indeed accompanied by enhanced proliferative tumor signals, and their distribution is spatially positively correlated, although weak (bottom)." (PMID 39716897, 2024). "We further explored specific communication pathways and discovered that signaling via PTPRM, MIF, MK, PECAM1, and SPP1 was markedly more active in the tumor group compared to the normal group." (PMID 39165361, 2024). "We observed that Non-Mit-CAF-C2 exhibited activation of the SPP1 signaling pathway, consistent with previous reports that SPP1+TAMs compromise tumor immunity and have a proangiogenic profile." (PMID 39835122, 2024). "Given the important role of the PMN in the metastatic colonization of tumor cells, we further investigated the potential effects of tumor-derived SPP1 on PMN formation and HCC lung metastasis." (PMID 39529085, 2024). "Emerging research has demonstrated the multifaceted roles of SPP1 in promoting tumor growth, regulating the tumor microenvironment, and its association with tumor metastasis and therapy resistance." (PMID 39143438, 2024). "It is widely acknowledged that the tumor-promoting role of SPP1 is performed through the modulation of cancer-related signaling pathways or the TME." (PMID 39726047, 2024). "We found that the expression of SPP1/ITGB1 signaling was more pronounced in the regions of tumor cells proximal to TAMs." (PMID 39207055, 2024).
tumor (continued). "In contrast, while focusing on the signals emitted from various macrophages to PCP tumor cells, SPP1, similar to ACP, primarily acted on each integrin family receptor of classical M2, targeting immune response and developing epithelial cells." (PMID 39483146, 2024). "The role of SPP1 was investigated in the tumor microenvironment (TME) of LUAD by the EMTome database and CIBERSORT algorithm to analyze TCGA data and determine the landscape of immune cell infiltration in LUAD." (PMID 38329443, 2024). "In summary, we demonstrate a connection between TGF-β, IL-6, TLR-2 and TLR-4 expression by the primary CRC tumor to SPP1 and FN1 expression in the metastatic intrahepatic tumor." (PMID 39372792, 2024). "IL-6 secreted from tumor enteric glial cells (EGCs) facilitates monocyte differentiation toward SPP1+TAMs." (PMID 38919629, 2024). "Enrichment of SPP1+ macrophages in tumor tissues is negatively correlated with lymphocyte infiltration, indicating poor survival and resistance to immunotherapy." (PMID 38685045, 2024). "To validate the significance of Macro_SPP1 infiltration, we analyzed data from the TCGA cohort and observed significantly upregulated infiltration of Macro_SPP1 in tumor samples compared to adjacent normal tissues." (PMID 38521868, 2024). "Third, while tumor cell population in the most dominant cluster (cluster Spp1 + ) decreased after anti-PD-1 treatment in wild-type tumors, the same population expanded in DRG2-depleted tumors after anti-PD-1 treatment." (PMID 38802348, 2024). "In particular, ligand-receptor pair analysis revealed that the SPP1 signal was mainly involved in the interaction among tumor-associated macrophage (TAM), T cells, and malignant cells via SPP1–CD44 and SPP1–(ITGA5 + ITGB1) ligand-receptor pairs." (PMID 38282028, 2024). "Simultaneously, KM analysis depicted that OS differed for SPP1 between tumor and normal samples, thereby suggesting that SPP1 can be used as a new therapeutic target against HCC." (PMID 38123874, 2024). "The results showed that it is possible to predict the status of tumor cells utilizing functional clonality and immune response by measuring SPP1 expression." (PMID 38355603, 2024). "Up-regulation of SPP1 expression in tumour tissue and serum of a variety of tumours correlates with poor patient prognosis." (PMID 38886539, 2024). "The authors used scRNA-seq on CCA cells from fourteen patients with iCCA and non-tumor liver tissues to identify S100P and SPP1 as markers for various types of iCCA." (PMID 39410050, 2024). "SPP1 was identified in the top regulated pathway “matrix organization” and was also among the top two up-regulated genes in tumor ECs with higher immunosuppressive scores revealed by scRNA-seq analysis of mouse GBM tumors." (PMID 38416830, 2024). "The Spp1+ TAMs, a subtype of TAMs that provokes immunosuppression, were dominantly enriched in Ero1aWT tumors compared with Ero1aKO counterparts, in accordance with the view that tumor cells were the primary driver for SPP1+ TAMs." (PMID 37769655, 2023). "It suggested that the tumor immune barrier (TIB) structure consisting of SPP1+ macrophages and CAFs near the tumor boundary affected the therapeutic efficacy of ICIs." (PMID 37007125, 2023). "Previous studies have shown that SPP1 + macrophages have immunosuppressive properties that prevent cytotoxic lymphocyte infiltration into the tumor core, serving as potential targets for tumor growth and metastasis." (PMID 37664173, 2023). "CD44 was the most widely known receptor of SPP1, mainly found on T cells (black box) and tumor cells (black arrow)." (PMID 37336873, 2023). "Consistent with human tissue, SPP1+ states were enriched in all three mouse tumor models relative to normal colon, and C1QC+ states were suppressed in all three tumor models." (PMID 38036590, 2023). "SPP1 is a secreted glycoprotein with multifunction such as immune regulation, cell survival, and tumor progression." (PMID 37656377, 2023).
tumor (continued). "Except for two subtypes with too few cells (Retnla+ macrophages and Hcar2+ macrophages), we found that the subtypes mainly existing in tumor tissues were more tended to M2 polarization, including the Spp1+, Clqb+, Ifitm6+, and Facn1+ macrophages." (PMID 36718369, 2023). "It has been reported that SPP1 regulates the anchorage-independent growth of tumor cells, invasion and chemo-resistance." (PMID 38067407, 2023). "Future studies should further elucidate how mCAFs and SPP1+ TAMs participate in tumor metastasis/progression and identify potential therapeutic targets." (PMID 37853464, 2023). "CCL18+ macrophages with high expression of CD163, MARCO, and CSF1R also exhibited stronger tumor-promoting effects than SPP1+ macrophages." (PMID 38347955, 2023). "Current evidence suggests that SPP1+ macrophages enhance tumor growth through TME matrix remodeling and exhibit upregulated glycolysis metabolism." (PMID 37187751, 2023). "In seven pairs of specimens from individuals with LIHC, qRT-PCR and IHC analysis revealed high SPP1 expression in tumor tissue, while FLT3, SOCS2 displayed the reverse trend." (PMID 37346073, 2023). "CDH2, SPP1, and TNC maintained a statistically significant increase associated with the progression of individual cancer stages in LUAD tumor samples compared to their respective controls." (PMID 37887075, 2023). "L–R interaction analysis further allowed us to identify proximal enrichment of interactions involving Spp1 or Fn1, which were previously found to be associated with CRC tumor progression." (PMID 38012149, 2023). "In liver tumors, scRNA-seq analysis identified three pro-tumor TAN subsets (CCL4+ TANs, IFIT1+ TANs, and SPP1+ TANs) and one anti-tumor subset (APOA2+ TANs)." (PMID 38066642, 2023). "SPP1+ TAM subpopulation has multiple roles in tumor development such as tumor metastasis, angiogenesis, tumor stem cell activation and immunosuppression." (PMID 38347955, 2023). "SPP1 is a significant component of the extracellular matrix, secreted by many kinds of cell types including osteoclasts, fibroblasts, immune cells, and tumor cells." (PMID 37188183, 2023). "We observed macrophages present in histologically normal colonic epithelium were more likely to be HLA-DQA1+ (a proxy marker for the C1QC+ state), while those present in tumor tissue were more likely to be SPP1+." (PMID 38036590, 2023). "Based on the key regulatory signals in the macrophage-tumor cell regulatory network, we performed a pseudotime analysis of the macrophages and found that signal molecules (TIMP1, VEGFA, SPP1) are highly expressed in immunosuppression-associated macrophages." (PMID 37189418, 2023). "The IFIT1+, SPP1+ and CCL4+ TANs were identified as pro-tumour, were associated with a poorer prognosis and had the highest levels of PD-L1 expression." (PMID 37534829, 2023). "Actually, SPP1 has been reported as a potential prognostic and immunotherapy biomarker, and correlated with tumor-infiltrating immune cells in multiple cancers." (PMID 36752296, 2023). "For example, SPP1+TAMs promoted tumor growth and proliferation by secreting collagen and insulin-like growth factor-1 (IGF-1)." (PMID 38347955, 2023). "Targeting the Spp1-Cd44 axis restored T cell function in vitro and significantly reduced tumor burden when treated with either anti-Spp1 or anti-Cd44 antibody alone or in combination with anti-Pd-1 antibody in the mouse model." (PMID 37336873, 2023). "Lastly, CD8EX cells in C12 exhibited high expression of Irf8 and Spp1 that in 4T1 tumors have been associated with balancing generation of antigen-specific CD8+ T cells and tumor rejection." (PMID 37620372, 2023). "SPP1 is a protein-coding gene that is upregulated in HCC with a close relation to the tumor process." (PMID 36650832, 2023).
tumor (continued). "In the present study, we performed the complex analysis of mRNA and protein expression of crucial regulators of tumor angiogenesis and tumor progression, expressed by tumor-associated macrophages (TAMs): S100A4, SPP1 and SPARC." (PMID 36895491, 2023). "SPP1 is also expressed by cancer cells, and previous studies have demonstrated correlations between levels of circulating SPP1 and/or increases in SPP1 expression on tumor cells and poor prognosis in many types of cancer." (PMID 37190178, 2023). "Markers of SPP1+MAM+, tumour-associated macrophages (TAMs), lipid-associated macrophages (LAMs), disease-associated microglia (DAM), and scar-associated macrophages (SAMs) are indicated in the heatmap." (PMID 37706477, 2023). "SPP1+ macrophages tend to accumulate at the tumor boundary and participate in the formation of the TIB structure, which excludes T cells from infiltrating the tumor core." (PMID 37896221, 2023). "We observed a large number of senescent tumor cells around the SPP1+ macrophages, whereas there were fewer SPP1+ macrophages and senescent cells in low-grade tumors and benign colon tissues." (PMID 37090726, 2023). "Although both groups of tumors involved SPP1+ and C1Qs+ TAMs, their distributions were found to be specific to the tumor origins." (PMID 36671569, 2023). "The result showed that SPP1 was increased not only in LIHC tumor tissue, but also in multiple cancers, such as BRCA, COAD, KIRP, LUAD, LUSC, READ and so on." (PMID 37386390, 2023). "Our data demonstrated that among patients expressing high cytoplasmic SPP1 levels, 78% of them are Stage Ta and T1 and only 22% of the patients have a high tumor stage (T2 and T3)." (PMID 38067407, 2023). "We were able to find only one study describing the co-localization of CD68 and SPP1 in tumor stromal components in human CRC." (PMID 36895491, 2023). "A larger number of SPP1 (red)-positive macrophages (green) and surrounding senescent tumor cells (p21 positive, pink) were observed in high-grade tumors than in low-grade tumors." (PMID 37090726, 2023). "Both mCAF and SPP1+ TAMs were mainly enriched in tumor tissues, and in many identical cancer hallmarks, such as EMT, angiogenesis, TGF-β, IL-6/JAK-STAT3, and TNF-α/NF-κB signaling pathways." (PMID 37853464, 2023). "The correlations between levels of circulating SPP1 and/or increases in SPP1 expression on tumor cells had poor prognosis in many types of cancer." (PMID 38347955, 2023). "C5AR1-RPS19, LGALS9-HAVCR2, and SPP1-PTGER4 between macrophages and CD8+ T cells, associated with CD8+ T-cell dysfunction, immunosuppressive status, and tumor advanced progression, were revealed in subTME-IS." (PMID 38002057, 2023). "Using CRC tumor tissues, we discovered that SPP1+ macrophages were surrounded by a large number of senescent tumor cells in high-grade tumors." (PMID 37090726, 2023). "SPP1 is also expressed by cancer cells, and previous studies have demonstrated correlations between levels of circulating SPP1 and/or increased SPP1 expression on tumor cells and poor prognosis in many types of cancer." (PMID 37190178, 2023). "In Hepa1-6 implanted tumor-bearing model, anti-Spp1 monoclonal antibody (mAb), anti-Cd44 mAb, or anti-Pd-1 mAb alone significantly inhibited the growth of tumors." (PMID 37336873, 2023). "The SPP1 is involved in processes like wound healing and angiogenesis and is relevant to tumor prognosis." (PMID 37187751, 2023). "There is a rich literature available substantiating that SPP1 derived from macrophages promotes cancer malignancy, tumor progression, and immune escape and contributes to worse clinical course and chemo-resistance." (PMID 37187751, 2023). "In tumour samples, the intercellular interactions were mainly active in signalling pathways, including pathways involving SPP1, VTN, NOTCH, THY1, and CD46." (PMID 36860314, 2023).